KIF1C (kinesin family member 1C)
Description:
Motor required for the retrograde transport of Golgi vesicles to the endoplasmic reticulum. Has a microtubule plus end-directed motility.
Synonyms: SPAX2; SPG58; LTXS1; SATX2; SAX2
Tractability: PROTAC: ubiquitination databases record sites on it; its protein half-life has been measured.
Gene: Protein-coding gene on chromosome 17 (4,997,722 to 5,028,401, forward strand). Ensembl gene ENSG00000129250.
Subcellular location: Cytoplasm, cytoskeleton
Subcellular location (Human Protein Atlas): Nucleoli; Nucleoplasm; Principal piece
Pathways (Reactome):
Hemostasis: Kinesins
Vesicle-mediated transport: COPI-dependent Golgi-to-ER retrograde traffic
Gene Ontology:
Molecular function: protein binding; RNA binding; cytoskeletal motor activity; plus-end-directed microtubule motor activity; ATP binding; microtubule binding; microtubule motor activity
Biological process: anterograde neuronal dense core vesicle transport; retrograde neuronal dense core vesicle transport; retrograde vesicle-mediated transport, Golgi to endoplasmic reticulum; vesicle-mediated transport; microtubule-based movement
Cellular component: axon; dendrite; endoplasmic reticulum; Golgi apparatus; kinesin complex; axon cytoplasm; cytoskeleton
Genetic constraint (gnomAD): Loss-of-function variants: 59 observed, 120.38 expected, observed/expected ratio (o/e) 0.49, 90% interval 0.4 to 0.61. The upper end of that interval is the gene's LOEUF score, 0.61, which puts it in group 2 of 6, group 1 being the genes least tolerant of losing a copy. Missense variants: 1,314 observed, 1,444.7 expected, observed/expected ratio (o/e) 0.91, 90% interval 0.87 to 0.95. Synonymous variants: 640 observed, 556.6 expected, observed/expected ratio (o/e) 1.15, 90% interval 1.08 to 1.23.
Homologues: Orthologues: chimpanzee KIF1C (99% identical), macaque KIF1C (99% identical), rabbit KIF1C (95% identical), pig KIF1C (95% identical), dog KIF1C (94% identical), guinea pig KIF1C (94% identical), rat Kif1c (94% identical), mouse Kif1c (94% identical), tropical clawed frog kif1c (71% identical), zebrafish kif1ca (26% identical), zebrafish kif1cb (17% identical). Paralogues in human: KIF1B (54% identical), KIF1A (53% identical), KIF13A (34% identical), KIF13B (33% identical), KIF16B (30% identical), KIF14 (28% identical), KIF17 (19% identical), KIF21B (19% identical), KIF3B (19% identical), KIF21A (19% identical), KIF7 (18% identical), KIF27 (18% identical), and 29 more.
Diseases named in the same sentence as KIF1C in open-access papers:
KIF1C is named in the same sentence as 45 diseases in open-access papers, as found by Europe PMC text mining. Sharing a sentence is not in itself a finding about the gene and the disease. The quoted sentences say what the papers report.
Ataxia (6 papers, 2018 to 2025). Ataxia refers to impaired coordination of voluntary muscle movement. "The most frequent causal genes were associated with spastic ataxia (SACS and KIF1C) and with ataxia and neuropathy or AOA (PNKP)." (PMID 35326432, 2022). "We can now report that progressive ataxia of Charolais cattle results from a homozygous single nucleotide polymorphism in the coding region of the KIF1C gene." (PMID 30067756, 2018). "Here, we report that progressive ataxia of Charolais cattle results from a homozygous single nucleotide polymorphism in the coding region of the KIF1C gene, leading to a functional knock-out of this gene and therefore mimicking some of the mutations in humans." (PMID 30067756, 2018). "Pathogenic variants in KIF1C cause Spastic Paraplegia 58 (SPG58), typically presenting with cerebellar ataxia and spastic paraparesis." (PMID 41236093, 2025). "The most frequent genes were those associated with spastic ataxia, ataxia, and neuropathy or AOA: SACS (4 families, 21.1%), KIF1C (2 families, 10.5%), and PNKP (3 families, 15.8%); the remaining genes were identified in single families only." (PMID 35326432, 2022). "In conclusion, most of the suspected ataxia cases (60/70) were homozygous for the KIF1C G>A substitution, including the histopathologically confirmed cases." (PMID 30067756, 2018). "Since kif1c knock-out mouse do not display any neurological symptoms, progressive ataxia of Charolais cattle thus provides a useful model for studying SPG58/SPAX2 and other demyelinating diseases." (PMID 30067756, 2018).
melanoma (4 papers, 2023 to 2026). A malignant, usually aggressive tumor composed of atypical, neoplastic melanocytes. "Interestingly, the mRNA of motor protein KIF1C, a component of the Kinesin superfamily like Kif5b, interacts with its encoded protein, localizing asymmetrically in protruding end of melanoma cells." (PMID 41163196, 2025). "Whether KIF1C is also serving in this role in melanoma cells or interfaces with actin to serve another role remains to be determined." (PMID 36859340, 2023). "The pictures of immunofluorescence on HCT116 human colon cancer cells, AC16 human cardiomyocytes, B16 mouse melanoma cells, and FMC84 mouse cardiomyocytes showed that the endogenous KIF1C is located in both the nucleus and cytoplasm too." (PMID 37452081, 2023). "By using a yeast two-hybrid screening, we identified Kinesin Family Member 1C (KIF1C), a protein involved in regulating podosome and invadopodium elongation, as a novel binding partner of KRIT1, and the interaction was confirmed in melanoma and epithelial cancer cells." (PMID 42074063, 2026).
breast carcinoma (3 papers, 2020 to 2023). "The KIF1C variant was identified in three assayed breast cancer cases, but they were not related to the original variant-carrying pair, nor to each other." (PMID 38136396, 2023). "Kinesins KIF1C and KIFC3 promotes breast cancer cell growth and survival and mediate taxane resistance." (PMID 32873298, 2020).
hereditary spastic paraplegia (3 papers, 2018 to 2025). Hereditary spastic paraplegias (HSP) comprise a genetically and clinically heterogeneous group of neurodegenerative disorders characterized by progressive spasticity and hyperreflexia of the lower limbs. "Two KIF1C mutations causing hereditary spastic paraplegia permit fast and processive single-molecule motility but are severely impaired under load." (PMID 35961316, 2022). "In humans, KIF1C mutations account for spastic ataxia SPAX2 or complex hereditary spastic paraplegia SPG58." (PMID 30067756, 2018).
progressive ataxia (3 papers, 2018 to 2024). "Progressive ataxia is a disease caused by an alteration in the gene Kinesin Family Member 1C (KIF1C)." (PMID 33329738, 2020). "We report herein that progressive ataxia of Charolais cattle, a neurodegenerative disease with autosomal recessive inheritance, is caused by a substitution in the KIF1C gene, which leads to a functional knock-out." (PMID 30067756, 2018). "In addition, we performed a survey among farmers on the awareness of progressive ataxia in Charolais cattle and how they take care to prevent dissemination of the mutated KIF1C allele." (PMID 38338009, 2024). "We assume from the literature and our data that the KIF1C A allele is not present in dairy breeds; therefore, it is very unlikely that cases of progressive ataxia may be found in the progeny of this German Angus bull." (PMID 38338009, 2024).
spastic ataxia (3 papers, 2018 to 2022). "We took advantage of the existence of this natural model, firstly to determine the cytological process of the demyelination lesions associated with KIF1C mutation and, secondly, to provide an animal model to study spastic ataxia failure." (PMID 30067756, 2018). "The first clinical signs observed in KIF1C mutated bovine were often an ataxic gait associated with weakness of the hind limbs, reminiscent of spasticity, which progressed slowly to the typical phenotype of spastic ataxia and ultimately led to recumbency." (PMID 30067756, 2018). "In this study, there was no causative mutation associated with spastic ataxia, such as SACS/VAMP1/KIF1C/MARS2/MTPAP/AFG3L2(AR), detected." (PMID 35572931, 2022).
Autoimmunity (2 papers, 2012 to 2023). The occurrence of an immune reaction against the organism's own cells or tissues. "Genetic variation in kinesins has also been linked to susceptibility to autoimmunity: specifically, variants in KIF21B and KIF5A have been associated with multiple sclerosis in humans, while variants in KIF1C predispose mice to autoimmune orchitis." (PMID 37895021, 2023).
glioma (2 papers, 2012 to 2023). A benign or malignant brain and spinal cord tumor that arises from glial cells (astrocytes, oligodendrocytes, ependymal cells). "In the majority of glioma cell lines, 3 genes were overexpressed: KIF1C, KIF3C, and KIF21B." (PMID 23320178, 2012).
prostate carcinoma (2 papers, 2023). A carcinoma that arises from epithelial cells of the prostate gland. "In primary cancer, KIF1C (Kinesin family member 1C) was differentially expressed according to T‐stage in primary prostate cancer." (PMID 37591798, 2023).
spastic ataxia 2 (2 papers, 2018 to 2024). "The clinical findings are compatible with “Spastic ataxia 2, autosomal recessive” caused by variants in the KIF1C gene." (PMID 38587696, 2024). "Mutations in KIF1C are responsible for autosomal recessive spastic paraplegia type 58 (SPG58) and spastic ataxia 2 (SPAX2)." (PMID 30067756, 2018). "Recently, mutations in KIF1C were associated with human spastic paraplegia type 58 (SPG58) and spastic ataxia 2 (SPAX2), where the radiological brain examination showed demyelination features." (PMID 30067756, 2018).
autoimmune oophoritis (1 paper, 2024). Autoimmune oophoritis is a rare cause of primary ovarian insufficiency (POI). "We did find one previous report implicating KIF1C mutations in an experimental model of autoimmune oophoritis, though the precise mechanism of action was not completely clear." (PMID 38726004, 2024).
autosomal dominant spastic paraplegia (1 paper, 2018). "KIF5A mutations account for autosomal dominant spastic paraplegia (SPG) 10, mutations in KIF1A lead to autosomal recessive SPG30 or to autosomal dominant cases of complex HSP and mutations in KIF1C have been found in autosomal recessive SPG58/SPAX2." (PMID 30067756, 2018).
brainstem atrophy (1 paper, 2022). "Regarding imaging, notably, family AR96 (KIF1C) showed basal ganglia hypointensities on T2/FLAIR sequences and AR111 (KIF1C) had brainstem atrophy." (PMID 35326432, 2022).
demyelinating disease (1 paper, 2018). A broad group of disorders that affect the myelin sheaths that cover the neurons. "Furthermore, our findings highlight the role of KIF1C protein in preserving the structural integrity and function of myelin and this model will provide useful information for other demyelinating diseases." (PMID 30067756, 2018).
myxoma (1 paper, 2023). A benign soft tissue neoplasm characterized by the presence of spindle and stellate cells, lobulated growth pattern, and myxoid stroma formation. "The CCDS of KIF1C (CCDS11065) was sequenced in cDNA samples that were extracted from myxoma tissues in patients without PRKAR1A variations in the validation group." (PMID 37452081, 2023). "RNA-seq of the two myxoma tissues and a normal atrial tissue showed that the expression of CYP1A2 was at an extremely low level without any change, while the expression of KIF1C was at a moderate level with an average decrease of 66% in myxoma tissues." (PMID 37452081, 2023). "And the immunoblotting figures showed the expression of KIF1C and PRKAR1A in all myxoma tissues was lower than that in normal atrial tissues." (PMID 37452081, 2023).
neuroblastoma (1 paper, 2023). Neuroblastoma (NB) is the most common solid, extracranial childhood tumor. "To determine whether AURKB, BUB1, and KIF1C are MYCN target genes, we performed ChIP-PCR and demonstrated a 4-to-10-fold enrichment of MYCN binding to the promoter regions in two MYCN-amplified neuroblastoma cell lines." (PMID 37958555, 2023).
prostate tumor (1 paper, 2023). "KIF1C regulation has recently been associated with invadopodia, suggesting that KIF1C may be associated with prostate tumor invasion and metastasis." (PMID 37591798, 2023).
tumor (5 papers, 2021 to 2023). "Whether KIF1C directly participates in tumor-related downstream signal transduction through the strictly conserved phosphorylated threonine residues of the FHA domain is also worthy of study." (PMID 37452081, 2023). "Therefore, will KIF1C exert its potential tumor-suppressing function via transcriptionally regulating PRKAR1A?" (PMID 37452081, 2023).
cancer (4 papers, 2023 to 2024). A tumor composed of atypical neoplastic, often pleomorphic cells that invade other tissues. "In the blue module (associated with the untreated cancer cells), the enriched pathways were “Cilium Disassembly”, “Microtubule”, “Tubulin Binding”, “Myosin Binding”, and “Lamellipodium Assembly”, where the genes KIF1C, MAP4, ACTG1, ABLIM3, TRIOBP are involved." (PMID 38534323, 2024). "In cancer cells, KIF1c can be activated by c-Src to mediate the formation of invadopodia, required for cell invasion." (PMID 38726004, 2024). "Different types of variations all lead to decreased mRNA levels of KIF1C relative to normal samples, and the mRNA level of KIF1C in different cancer samples is also lower relative to normal samples." (PMID 37452081, 2023).
neurodegenerative disease (3 papers, 2010 to 2025). A disorder of the central nervous system characterized by gradual and progressive loss of neural tissue and neurologic function. "A homozygous loss-of-function mutation within the KIF1C gene (c.608G>A) was found to be responsible for this neurodegenerative disease." (PMID 38338009, 2024). "We show that loss of KIF1C leads to widespread changes in this composition and unravels transcriptomic changes that may be relevant for other neurodegenerative diseases." (PMID 40495808, 2025). "Importantly, genes and TFs dysregulated due to KIF1C loss may also be implicated in other neurodegenerative diseases." (PMID 40495808, 2025). "Therefore, spatial dysregulation of transcription due to KIF1C loss may uncover transcriptional changes also relevant in other neurodegenerative diseases." (PMID 40495808, 2025). "We found that several key factors crucial for survival and health were absent in KIF1C-KO axons, highlighting a possible role of these also in other neurodegenerative diseases." (PMID 40495808, 2025).
genetic disorder (1 paper, 2025). "KIF1C, a kinesin family member, is implicated in HSP, a group of heterogeneous genetic disorder resulting in degeneration of upper MN axons." (PMID 40495808, 2025).
KIF1C also shares sentences with these, for which no sentence is quoted: Spastic paraplegia (2 papers); amyotrophic lateral sclerosis (1); Arthritis (1); atherosclerosis (1); bladder cancer (1); cerebellar ataxia (1); Cognitive impairment (1); colon cancer (1); developmental delay (1); Dystonia (1); Friedreich ataxia (1); influenza infection (1); Limb tremor (1); liver cancer (1); mental disorder (1); multiple sclerosis (1); neurological diseases (1); neuropathy (1); PEHO syndrome (1); periodontitis (1); rheumatoid arthritis (1); Spastic paraparesis (1); Tremor (1); type 1 diabetes (1).